MUC1 (mucin 1, cell surface associated)
Diseases named in the same sentence as MUC1 in open-access papers (continued):
Sharing a sentence is not in itself a finding about the gene and the disease.
tumor (continued). "Further, the combination of vaccinia expressing the tumor antigens CEA and Muc1 (Panvac-v) and fowlpox virus expressing the same tumor antigens (Panvac-f) has been shown to improve direct lysis and immune-mediated tumor destruction." (PMID 28955655, 2017). "Proliferation of the dual MUC1/ErbB2 CAR T cells required coexpression of MUC1 and ErbB2 on target tumor cells, and the CAR T cells were effective in killing ErbB2(+) tumor cells." (PMID 29312333, 2017). "In CK19 and sialylated MUC1 positive sample, fluorescence double-staining indicated that coexpression of CK19 and sialylated MUC1 was confirmed in some tumor cells." (PMID 28325920, 2017). "Comparing tumor free tissue with controls showed higher expression of CIDEC, MUC1 and ZBTB16 in the majority of tumor free samples." (PMID 28038473, 2017). "Syndecan-1 (CD138), MUC-1 (CD227) CD45, CD34, and the putative cancer stem cell markers CD15, CD24, CD44, and CD133 surface expression were evaluated on CSF floating tumor cells." (PMID 28399903, 2017). "Although cumulative doses of 4 and 10 Gy were found to be sublethal, they were still able to enhance T cell-mediated lysis of each tumor cell line by CTLs specific for MUC-1, brachyury, and CEA tumor antigens." (PMID 27893426, 2016). "As expected, we found that gene expression patterns are different in PC tumor samples compared to normal, undiseased peritoneum with a number of genes differentially regulated: BAG1, CCNB1, CD44, CLDN4 and 6, MMP2, MKI67, MUC1, MYBL2, and SERPINB3." (PMID 27542596, 2016). "Surprisingly, they found a strong IgG response capable of binding to MCF-7 tumor cells, whereas they and others found low immunogenicity in their earlier investigations with the BSA vaccine containing MUC1-STn." (PMID 27472370, 2016). "Most of the tumor samples analyzed (> 90%) expressed very high levels of CA125, FOLR1, EPCAM and MUC-1 and intermediate levels of Her-2/neu, similarly to the OVCAR-3 cell line." (PMID 27323861, 2016). "In a next step, we characterized all currently available human tumor models for ACC for Ki67, SF-1 and EGF-receptor status in comparison with MUC-1-xenografts." (PMID 27764813, 2016). "Immune responses to additional tumor antigens included PSMA (prostate-specific membrane antigen), PAP (prostatic acid phosphatase), MUC-1, and Brachyury." (PMID 26961085, 2016). "Whereas the mechanism identified in this manuscript identifies aspects of the biology of MUC1 in modulating transcriptional effects, our in vivo and in vitro studies suggest FRA-1 can independently contribute to effects on tumor progression." (PMID 27220889, 2016). "The MUC1 network also possesses APC1, JUP, and PRKCD genes that display tumor suppression functions, which are also co-amplified." (PMID 27825118, 2016). "As expected, most of the tumor samples analyzed (> 90%) expressed very high levels of CA125, FOLR1, EPCAM and MUC-1 and elevated levels of Her-2/neu, similarly to OVCAR-3 cell line." (PMID 27323861, 2016). "More than 90% of tumor samples expressed very high levels of CA125, FOLR1, EPCAM and MUC-1 and elevated levels of Her-2/neu, similarly to OVCAR-3 cell line." (PMID 27323861, 2016). "A subset of primed MUC1-specific CD4+ T cells induced by DC/MUC1-positive tumor FCs possesses cytotoxicity against MHC class I- and MUC1-positive tumor cells." (PMID 27240347, 2016). "In this context, mucin 1 (MUC1), an oncoprotein that is aberrantly expressed in human cancers, is a translational target of PDCD4, suggesting that PDCD4 acts as a tumor suppressor by inhibiting oncoprotein translation." (PMID 27542230, 2016). "Our previous study found that MUC1 gene silencing inhibited the growth of SMMC-7721 cells in vitro and in vivo, and MUC1 shifted Smad3 signaling from a tumor-suppressive to an oncogenic function in MUC1-overexpressing HCC cells." (PMID 26057631, 2015).
tumor (continued). "3D-CSC subsets from in vivo tumor of control group manifest synchronous expression of TERT, CD29, CD44, CD90, CD105, CD133 and MUC-1 for renewable potential under spheroid-flow immunofluorescence scan." (PMID 26512920, 2015). "Prior to metastasis establishment, plentiful CSC-subsets (MUC-1+, CD44+, CD133+) with migrating potential were detected to drift from local tumor into the sentinel LNs (SLN) via natural lymph flux assay in dilated lymphatics/sinus in control group." (PMID 26512920, 2015). "Among them, mucin 1 (MUC1) seems to be the most studied and promising tumor marker and recently, it was described as a target for therapy." (PMID 26022333, 2015). "Previous studies found MUC1 was usually over expressed in CRC tissue and seemed to play a role in the tumor development and progression." (PMID 26367866, 2015). "Immunohistochemical staining showed that MUC1, p-JNK, pSmad3L and c-Myc expression were highly positive in tumor tissues from the SMMC-7721 or NC groups but were weakly positive or even negative in tumor tissues from the MR1-D4 and MR1-D9 groups." (PMID 25714018, 2015). "Both MUC1 and p-JNK/pSmad3L/c-Myc expression were highly positive in tumor tissues but weakly positive in normal liver tissues." (PMID 25714018, 2015). "This is the first feasibility study which investigated anti-MUC1 antibody in NAF and its relationship with tumor characteristics." (PMID 26693201, 2015). "Collectively, these results indicate that MUC1 shifts Smad3 signaling from a tumor-suppressive pSmad3C/p21WAF1 to an oncogenic pSmad3L/c-Myc pathway by directly activating JNK in HCC cells, suggesting that MUC1 is an important target for HCC therapy." (PMID 25714018, 2015). "The results demonstrated that Tri-Ad5–infected human DCs can generate T cells capable of lysing, in an MHC-restricted manner, human tumor cells that endogenously express brachyury, CEA, and MUC1." (PMID 26374823, 2015). "Western blotting and immunohistochemistry confirmed the upregulation of MUC1 and MUC4 in resistant cells and their corresponding tumor xenografts at the protein levels respectively." (PMID 25327561, 2014). "This pattern differs from the expression patterns involving MUC1, MUC2 or MUC4 that are related to a poor prognosis in neoplasms of other organs." (PMID 24722639, 2014). "We did not observe any changes in levels of amylase or cytokeratin 19, or the mucins MUC1, MUC2 or MUC5AC in rapamycin-treated KC PTEN tumours." (PMID 24717934, 2014). "Immunohistochemical staining revealed positivity of the tumor cells for Pan-CK, CK7, CK8/18, MUC1, MUC6, CD10, carbonic anhydrase IX and EMA." (PMID 24443801, 2014). "The mean percentage of positive carcinoma cells in tumour tissue was 74% for KOC, 75% for S100P, 73% for mesothelin and 75% for MUC1." (PMID 25071419, 2014). "In human PDA, MUC1, and COX-2/PGE2 pathways are highly activated and patients have high levels of MDSCs in the tumor, spleen, and blood, thus our data has high clinical relevance as future therapies can be designed to target MUC1 and COX-2 signaling." (PMID 24605110, 2014). "The mean tumour tissue versus mean normal tissue Histoscore for MUC1 was 193 vs. 48, while for S100P, KOC and mesothelin, the mean tumour tissue versus mean normal tissue Histoscores were 165 vs. 0.3, 150 vs. 0.5 and 115 vs. 4 respectively." (PMID 25071419, 2014). "Of these 9 patients, 4 had received intratumoral DC vaccine and 3 (75%) showed PR or SD, while in the remaining 2 patients exhibiting disease control, the antigens for DCs were a tumor lysate and WT1+MUC1, respectively." (PMID 24649223, 2013). "Together, these findings indicate that HLA-A2 restrictive MUC1-specific CTLs that kill PANC-1 cells are efficiently induced by combined OK-432- and PSK-activated DC/tumor in vitro." (PMID 23555011, 2013).
tumor (continued). "On normal epithelia, MUC1 VNTR are extensively O-glycosylated with long branched glycans, whereas on tumor cells they are markedly hypoglycosylated with simpler and shorter glycan chains." (PMID 24072600, 2013). "MUC1 and MUC4 stained the apical portion of glandular tumor cells and the membrane of intermediate and epidermoid tumor cells while MUC2 and MUC5AC stained the cytoplasm of glandular, mucous, and intermediate tumor cells." (PMID 24367734, 2013). "To identify proteins that interact with MUC1 responsible for carrying out important functions in tumor cells, we transfected the mouse tumor cell line RMA with cDNA coding for full-length MUC1 containing 22 tandem repeats in the VNTR domain (RMA-MUC1)." (PMID 24072600, 2013). "The extracellular domain of MUC1 contains a variable number of tandem repeats (VNTR) region that is extensively O-glycosylated in normal epithelia and underglycosylated in tumor cells." (PMID 24072600, 2013). "In a murine PC study, an MUC-1 DNA vaccine was able to induce a significant MUC-1-specific CTL response and had both prophylactic and therapeutic effects in tumor-bearing mice." (PMID 23509731, 2013). "In this study, MUC1/HSP70-coupled DNA increased the capacity of DC to induce effective cytotoxic T-cell responses and inhibited tumor cell growth." (PMID 23509794, 2013). "However, overexpression of MUC1 produced tumor of larger size compared to untrasfected B16 cells or the empty vector (EV) transfected cells, suggesting that MUC1 may modulate the rate of tumor growth (white arrow)." (PMID 24072600, 2013). "In verified metastasis, where there is a higher tumor load, a statistical agreement was verified between these assays, and CK-19 expression correlated with HER-2, GA733-2 and MUC-1." (PMID 23497487, 2013). "Most importantly, E-tumor/FCs activated T cells capable of producing high levels of IFN-γ, resulting in augmented MUC1-specific CTL induction." (PMID 23717436, 2013). "We showed that expression patterns of c-Met and MUC1 correlated with each other and with the differentiation status of HCC cell lines and tumor tissues." (PMID 22962849, 2012). "In the canine tumour cell lines CMT-W1, CMT-W2, CMT-W1M and CMT-W2M, we found a single protein band of MUC1 with a molecular weight similar to the higher human form." (PMID 22726603, 2012). "Positive expression of E-cad and MUC1 was localised to the cell membrane, and a combination of the plasmalemma and cytoplasm in NSCLC tumour cells, respectively." (PMID 22761930, 2012). "Altered expression of mucins such as MUC1 and MUC4 has been shown to regulate various processes such as tumour cell growth, cell adhesion, motility and tumorigenicity." (PMID 21326240, 2011). "The expression of MUC1, CD31, Ki-67, TUNEL and apoptotic proteins in tumor xenografts was evaluated by immunohistochemistry." (PMID 21931707, 2011). "The intensity of immunohistochemical staining of MUC1, CD31, Ki-67, TUNEL, Caspase-3 (Active) and PARP-1 (Cleaved p85) in tumor xenografts from combination test, combination control, MAb C595 control and vehicle control." (PMID 21931707, 2011). "MUC-1 and uPA are strongly expressed on CFPAC-1, PANC-1 and moderate expression was found CAPAN-1 cell clusters and tumor xenografts." (PMID 24212784, 2011). "Looking at the tumour grade, all the genes except MUC1 and SPP1 were significantly up-regulated in samples with a high tumour grade in Oncomine." (PMID 21314937, 2011). "Therefore, MUC1 may play a role in tumor invasion and metastases by disrupting cell adhesions." (PMID 20550696, 2010). "The pronounced differential expression of MUC-1 in tumor versus normal tissues has been used in experimental developments of antitumor therapies, including MUC-1 vaccines and MUC-1 promoter-restricted antitumor-specific viruses." (PMID 19635153, 2009).
tumor (continued). "In our initial study on DCs/tumor fusion cell vaccines, murine MC38 adenocarcinoma cells stably transfected with human MUC1 (MC38/MUC1) were fused to synergistic DCs derived from bone marrow in the presence of polyethylene glycol (PEG)." (PMID 20182533, 2009). "Analysis of surface markers during long term tumor culture of primary HBCEC (more than 476d) demonstrated a prominent expression of CD24, CD44 and MUC1 (CD227)." (PMID 19751512, 2009). "Heat-treated autologous tumor cells display a characteristic phenotype with increased expression of HSPs, carcinoembryonic antigen (CEA), MUC1, and MHC class I." (PMID 20182533, 2009). "In the present study, MUC1 and MUC4 expression identified a subgroup of patients that had a particularly poor prognosis among patients with a differentiated pancreatobility tumour." (PMID 19236510, 2009). "In this paper we report the use of three different STn-based immunogens, that are synthetic STn coupled to KLH (Theratope), MUC1-pep-STn coupled to KLH and MUC1-prot-STn, in a MUC1 transgenic mouse model to induce tumour protection." (PMID 19436292, 2009). "Interestingly, those patients with endogenous anti-MUC1 antibodies had a significantly higher probability of freedom from distant metastases, raising the possibility that the antibodies may be destroying circulating MUC1-positive tumor cells." (PMID 19811637, 2009). "The genes like CK19, muc1, PSE and EpCAM that show significant background expression in normal samples, loose its accuracy in tumor cell detection when Ficoll density gradient cell separation methodology is used." (PMID 18289390, 2008). "A novel vaccinia virus vectors expressing both tumor antigens CEA and MUC-1, and costimulatory molecules TRICOM (PANVAC-V) was constructed and used to prime an initial T-cell response." (PMID 18039393, 2007). "Previous studies have suggested a link between MUC1 and MUC3 expression and poor prognosis both in colorectal and other tumour types." (PMID 17349047, 2007). "The binding capacity of the anti-MUC1 antibody MB5 and the anti-CEA antibody CB37 were assessed by immunofluorescence staining of tumor cells directly with phage antibodies." (PMID 17945015, 2007). "These splice forms, called MUC1/Y, MUC1/X, MUC1/Z, MUC4/X, and MUC4/Y, present a growth factor-like architecture and are thought to be involved in fetal and tumour development." (PMID 15494719, 2004). "MUC1 was detected in PAC120 tumours, the anti-MUC1 antibody staining focally the cytoplasm of 10–20% of tumour cells." (PMID 14760390, 2004). "Recently, RT–PCR assays with tumour-specific gene markers such as CK19, CEA, MUC1, PIP, Mapsin and mammaglobin B have been widely used to detect occult metastasis in cancer patients." (PMID 14583780, 2003). "The expression of MUC1 and MUC4 membrane-bound mucins was detected in the cytoplasm (97% and 54% of all tumours, respectively) and in the apical membrane (91% and 60% of all tumours, respectively)." (PMID 39966658, 2025). "The high NPV of 95.7% for MUC1 expression in this study implies that a low MUC1 score (0/1) strongly indicates the absence of neoplasia, making it a valuable tool for ruling out malignancy in ambiguous cases." (PMID 40821195, 2025). "Apical membranes were not visible in 7% of tumours analysed for MUC1 and in 6% of tumours analysed for MUC4." (PMID 39966658, 2025). "Notably, a sex-dependent response emerged in mice vaccinated with MUC1 C3-liposomes with TLR agonists (TLR4, TLR7/8, and TLR9); male mice exhibited greater tumor suppression than females." (PMID 40284463, 2025).
tumor (continued). "The simultaneous administration of MUC1 mRNA and CTLA-4-targeting siRNA represents a dual immunotherapeutic strategy aimed at overcoming the immunologically “cold” tumor microenvironment characteristic of TNBC, a context in which such combined approaches have been explored only to a limited extent." (PMID 40943370, 2025). "Despite MUC1 involvement in many biological processes of PDAC carcinogenesis, it is improbable that inhibition of MUC1 alone may arrest the tumor progression." (PMID 40001578, 2025). "The continued development of PANVAC and other viral vector-based vaccines could provide a valuable therapeutic option, particularly for cancers that express well-characterized tumor antigens, like CEA and MUC1." (PMID 40333213, 2025). "In contrast, vaccination with free MUC1 peptide not encapsulated in liposomes did not reduce tumor growth in either sex." (PMID 40284463, 2025). "Importantly, targeted inhibition of either MUC1 or PP2A shifts CSLCs toward asymmetric division and suppresses tumor growth." (PMID 40349179, 2025). "Distinctive morphological features, such as frequent tubular architecture, and a characteristic immunoprofile (common MUC1 positivity and rare SSTR2 A expression, in addition to somatostatin expression and tumor location), help to identify ampullary Som-NETs among NF-Duo-NETs." (PMID 40347392, 2025). "However, when C3-liposomes were formulated with MUC1 and TLR agonists, the combination seemed detrimental, as it abolished the significant reduction in tumor growth seen in MUC1 C3-liposome-vaccinated mice." (PMID 40284463, 2025). "In summary, YBX1 promotes tumor progression through its transcription factor activity, exerting its effects via various downstream targets such as MUC1, CDC25a, NANOG, Kindlin-2, G3BP1, AURKA, SPP1, the EGFR-RAS-MAPK axis, CORO1C, among others, depending on the specific tumor type." (PMID 40799245, 2025). "MUC1 is a large membrane glycoprotein that is heavily glycosylated and restricted to the apical surface of epithelial cells; however, MUC1 in tumor cells is under-glycosylated and no longer restricted to the apical surface." (PMID 40227779, 2025). "However, in the Capan-2 C1GALT1 KO model or the Capan-2 model treated with itraconazole, where MUC1 levels were increased, CAR-T cells with Tn-MUC1 bridge exhibited significantly more anti-tumor activity compared to the CD19-bridge." (PMID 41372740, 2025). "Furthermore, combining etoposide with targeted inhibition of MUC1 (GO‐203) or PP2A (LB100) effectively reduced stemness in SCLC cells and significantly suppressed tumor growth." (PMID 40349179, 2025). "Although antigens such as MUC1 and PSCA are overexpressed in NSCLC, CAR-T cells targeting MUC1 failed to inhibit tumor growth in patient-derived xenograft models." (PMID 40904467, 2025). "We observed no sex differences in tumor volume in the MUC1 C3-liposome group that did not contain TLR agonists, with both sexes having significantly smaller tumors than PBS mice (female mice: p = 0.04, male mice: p = 0.01)." (PMID 40284463, 2025). "To confirm that CAPAN1 TAA expression was maintained in 3D cultures, we isolated tumor cells at two different time points (day 4 and 25) after spheroid formation and measured the expression of PSCA and MUC1, both of which were maintained throughout the culture period of 25 days." (PMID 40808942, 2025). "This combination exhibited strong antitumor effects, suggesting that the TR2.4-1BB receptor can augment CAR-T cell responses against both MUC1 and HER2 antigens, effectively eliminating MDSCs and leading to improved T-cell survival, proliferation, and persistence at the tumor site." (PMID 40281554, 2025). "Certain glycan epitopes of MUC1, such as the Tn‐antigen, TF‐antigen and their sialylated forms, are exposed during malignant transformation, and MGL receptor was shown to play a role as a recognition molecule on Mφs for tumor cells." (PMID 40033767, 2025).